AR (androgen receptor)
Diseases named in the same sentence as AR in open-access papers (continued):
Sharing a sentence is not in itself a finding about the gene and the disease.
prostate carcinoma (continued). "Importantly, T60 and its derivative T638 have also been shown to block the activity of the AR and the proliferation of AR-positive prostate cancer cells." (PMID 36678591, 2023). "Androgens via AR have been reported to increase and decrease ROS levels in prostate cancer cells." (PMID 37874216, 2023). "KLF functions as an AR activator and positively correlates with prostate cancer progression." (PMID 36672280, 2023). "Prostate cancer arises as an androgen receptor (AR)-driven disease." (PMID 37874216, 2023). "Predominantly, prostate cancer growth is propelled by androgen receptor (AR) signaling." (PMID 38001899, 2023). "This discovery was crucial because of AR’s significance in developing prostate cancer cells." (PMID 37110167, 2023). "Interestingly, the DNAJC16 gene is one of the chaperone families HSP40, which regulates AR and mediating sensitivity to chaperone inhibitors to aid in identifying new drug targets for efficacy in castration-resistant prostate cancer." (PMID 38136890, 2023). "Androgen Receptor (AR) inhibition is a nuclear receptor that belongs to the family of ligand-responsive transcription that governs the physiological activities of androgen and is almost always expressed in prostate cancer." (PMID 38004496, 2023). "In contrast, AR expression is detected in prostatic tumors even in the advanced stages, indicating that a loss of AR expression is not a clinical marker for prostate cancer." (PMID 37025180, 2023). "Prostate cancer cells are characterized by a hybrid glycolytic/oxidative phosphorylation (OXPHOS) phenotype determined by androgen receptor (AR) signaling that may stimulate the AMPK-PGC1α cascade." (PMID 36674430, 2023). "Our research presents compelling evidence to suggest that Rubia cordifolia (R.C.)may inhibit the growth of prostate cancer by disrupting AR and GR signaling." (PMID 37860121, 2023). "Notably, KDM4A-AS1 stabilized ubiquitin carboxyl-terminal hydrolase 14/androgen receptor complex to promote tumor growth in castration-resistant prostate cancer." (PMID 36973424, 2023). "Androgen binding to AR triggers a cascade of events that produce ROS signaling and promote LD accumulation and autophagy, which in concert promote metabolic and redox homeostasis that enable prostate cancer cell proliferation." (PMID 37874216, 2023). "RB1 deficiency and/or replication stress, characteristics of poor prognosis, and conferred sensitivity were associated with complete tumor regression in both neuroendocrine (NEPC) and androgen receptor positive (ARPC) prostate cancer models, even with low B7H3 levels." (PMID 37725435, 2023). "This is consistent with human breast cancer CNVs, which often affect a whole chromosome arm on either side of the centromere except in the cases of strong selective pressure over a particular region, such as the cases of ERBB2 in breast cancer or AR in prostate cancer." (PMID 37805590, 2023). "Because VCaP cells overexpress full-length AR and AR variants, and LNCaP cells express full-length AR only, differences in the effect of DNT on the androgen-dependent growth of prostate cancer cells may occur." (PMID 37744273, 2023). "The mainstay of treatment for advanced prostate cancer is targeting of androgen receptor signaling, including androgen deprivation therapy plus second-generation androgen receptor blockade (e.g., enzalutamide, apalutamide, darolutamide), and/or androgen synthesis inhibition (abiraterone)." (PMID 37228586, 2023). "In addition, we confirmed that pinostilbene is cytotoxic even in the Enz-resistant prostate cancer cell line 22Rv1), and that it reduces expression of ARv7 and full-length AR." (PMID 37794090, 2023). "It has been reported that promoting the interaction of AR with the PSA promoter by activating the JMJD2A/AR signaling pathway could lead to reduced apoptosis in prostate cancer cells." (PMID 37165308, 2023).
prostate carcinoma (continued). "As prostate cancer cell survival is highly dependent upon AR signaling, LTR40a induction might provide an alternative marker for disease detection." (PMID 36979914, 2023). "They express less AR as compared to metastasized prostate cancer cells." (PMID 37282627, 2023). "In addition to inhibiting DNA synthesis and modulating the AR signaling pathway, quercetin has additional anti-prostate cancer effects via AR." (PMID 38004496, 2023). "Emerging evidence highlights the significant role of selenium and selenoproteins in prostate cancer, encompassing AR signaling, antioxidative properties, cell death, cell cycle regulation, angiogenesis, epigenetic regulation, immunoregulation, epithelial–mesenchymal transformation, and redox signal." (PMID 37765058, 2023). "In addition to these targets, androgen receptor (AR) was also included for further simulations due to its important role in prostate cancer cell growth." (PMID 37687413, 2023). "With regard to AR positive prostate cancer, fewer mechanism-based studies have been performed." (PMID 37536629, 2023). "Moreover, SREBP-1 was reported to regulate AR promoter activity and transcriptional expression in prostate cancer cells." (PMID 37794090, 2023). "In addition to the androgen receptor, other NRs have been reported to contribute to prostate cancer proliferation and progression." (PMID 37524814, 2023). "PADI2 promotes protein stability and transcriptional activation of AR in prostate cancer cell line." (PMID 37228649, 2023). "Current or prior prostate cancer treatments with dates: ADT or other AR-targeted treatments." (PMID 36604326, 2023). "The Androgen receptor (AR) plays a pivotal role in prostate cancer." (PMID 37298192, 2023). "Targeted therapies based on AR are already in clinical practice in prostate cancer." (PMID 37925508, 2023). "Numerous isoforms of the AR protein are known to arise due to both internal translation initiation sites and alternative splicing, and isoform production has been shown to be linked to certain AR pathologies such as androgen insensitivity, SBMA, and prostate cancer." (PMID 37628685, 2023). "Dihydrotestosterone (DHT) and testosterone (T), which mediate androgen receptor nuclear translocation and target gene transcription, are crucial androgens and essential molecular triggers required for the proliferation and survival of prostate cancer cells." (PMID 36837903, 2023). "By binding to the ERβ, phytoestrogens may increase prostate cancer differentiation, not only directly, but also by downregulating the androgen receptor and thus androgen-driven proliferation." (PMID 37049632, 2023). "Additionally, the structure scaffold of silibinin and derivatives is distinguished from that of all currently marketed AR antagonists, making it possible to become a novel group of AR modulators for prostate cancer." (PMID 37111288, 2023). "P14ARF binds to the androgen receptor (AR) and suppresses transactivation in prostate cancer cells." (PMID 38132337, 2023). "Moreover, continued AR signaling despite the presence of antagonists and/or depletion of androgens drives antiandrogen resistance in prostate cancer." (PMID 36991452, 2023). "Moreover, the data suggest that the AR-mediated transcriptionalprogram also contributes to mesenchymal-to-epithelial transition (MET)in prostate cancer progression." (PMID 37720744, 2023). "In addition, treatment with enzalutamide (ENZ) and ARV-110, two anti-AR drugs, enhance the sensitivity of AR+ prostate cancer cells to ferroptosis by decreasing the expression of MBOAT2." (PMID 37739961, 2023). "Downregulation of NDRG1 in C4-2 and PC-3 prostate cancer cell lines promotes an increase in cell invasion and migration in cell culture, and suppression of AR/NDRG1 signalling has been suggested as a potential mechanism that promotes castrate-resistant prostate cancer (CRPC) progression." (PMID 36765657, 2023).
prostate carcinoma (continued). "In prostate cancer cells, the androgen receptor (AR) promoter was shown to be an epigenetic target of PRMT5, and knockdown of PRMT5 caused a reduction in H4R3me2 marks at the AR promoter and a subsequent reduction in AR expression." (PMID 37795443, 2023). "In pancreatic cancer, miR-301a may act as an oncogene by negatively regulating SAMD4 as its target, while in prostate cancer, miR-301a may be involved in metastasis through AR/TGF-β1/Smad/MMP9 signaling modulation." (PMID 37509289, 2023). "The findings of this study suggest that a distinct group of young patients with aggressive prostate cancer is frequently associated with TMPRSS2:ERG fusions, while exhibiting a lower likelihood of harboring mutations in other genes, such as AR, SPOP, and ASXL1." (PMID 37511059, 2023). "There is an increasing body of data regarding the anti-proliferative effects of AR stimulation in breast, ovarian, endometrial, and prostate cancers and cell culture models, and the complex role of androgens, including the extensive capacity for crosstalk between steroid receptors." (PMID 37190127, 2023). "However, several studies have exhibited a positive crosstalk between AR and NF-κB signaling in prostate cancer." (PMID 37047218, 2023). "Moreover, recent findings revealed that the androgen receptor (AR), which is among the main drivers of prostate cancer progression, is involved in cross-talk with proteins belonging to the MMP family." (PMID 38255186, 2023). "However, in late-stage prostate cancer and following androgen deprivation therapy, cancer cells adapt to low AR–androgen complex signaling and activate alternative signaling cascades leading to survival, proliferation, and metastasis." (PMID 37108576, 2023). "Prx1 also promotes prostate cancer growth by activating androgen receptor (AR) signaling." (PMID 37237480, 2023). "Moreover, the MAPK/ERK signalling pathway has been proposed as the central pathway for AR‐mediated non‐genomic regulation of prostate cancer cell proliferation." (PMID 37326412, 2023). "Finally, little is known about the mechanism by which prostate cancer cells hijack the expected response to androgen receptor suppression and become androgen-independent." (PMID 38033743, 2023). "ARV-110 is a CRBN-based PROTAC, which is designed to degrade AR for prostate cancer treatment." (PMID 37077823, 2023). "GAPDH could enhance the transcriptional activity of AR in prostate cancer cells, and PPIB could regulate cell-cycle related genes including CCDC74A which further promotes cell proliferation." (PMID 37729607, 2023). "This introduces a hypothesis that a sub-set of prostate cancers (equivalent to ~15%) have an evolutionary course that converges on an AR-mutant resistant genotype following hormone therapy." (PMID 37563129, 2023). "In vitro assays showed limited uptake in AR-positive DU-145 prostate cancer cells." (PMID 36677878, 2023). "Besides direct, also indirect crosstalk mechanisms can affect the therapy response, as shown for GR and AR in prostate cancer, where even diminished responsiveness to enzalutamide (anti-androgen) was observed." (PMID 37578563, 2023). "SRD5A protein was significantly decreased by FUS-Cav + HT treatment in prostate cancer cells, which might result in the inactivation of the AR signaling pathway and a reduction in cell survival." (PMID 37152995, 2023). "PADI2 is H3 arginine demethylase, a key mediator for AR in prostate cancer progression." (PMID 37228649, 2023).
prostate carcinoma (continued). "In occurrence with CHD1 deletion, SPOP mutations define a distinct prostate cancer subtype, characterized by genomic instability, increased AR transcriptional activity, absence of ERG rearrangements, and increased DNA methylation." (PMID 36776288, 2023). "Our results suggest that a DDGS diet may reduce AR synthesis by decreasing the concentration of testosterone, thus acting as a preventive agent against prostate cancer." (PMID 37445854, 2023). "Since HSP70 acts as a chaperone for multiple oncogenic proteins, inhibition of HSP70 may also inhibit prostate cancer cell proliferation through an AR-independent mechanism, which is a hypothesis that should be further investigated in future studies." (PMID 36773708, 2023). "Moreover, AR can induce DSB repair in prostate cancer cells, which prompted us to move on to a combination treatment with a PARP inhibitor and androgen receptor signaling inhibitors (ARSIs) for patients with CRPC." (PMID 37174127, 2023). "SRD5A1 and SRD5A3 were the primary isozymes in the prostate cancer cells, and suppression of SRD5A1 and SRD5A3 protein levels was reported to be a promising alternative therapy to block the AR signaling pathway and inhibit the growth of malignant prostate tumors." (PMID 37152995, 2023). "One such cross-talk can represent AhR-mediated AR degradation, since AhR has been demonstrated as a ligand-dependent E3 ubiquitin ligase that induces proteasomal degradation of AR in the androgen-sensitive prostate cancer cell line LNCaP." (PMID 36613955, 2022). "Our aim was to investigate the AR/NF-κB axis in more detail by using two different human prostate cancer cell lines, as well as a mouse model of prostate cancer, experimentally and to combine that with computational meta-analyses of several publicly available datasets." (PMID 36551650, 2022). "However, further investigation is needed to evaluate the specificity and efficiency of CRISPR-Cas13 for AR targeted therapy specifically in the context of prostate cancer." (PMID 35864113, 2022). "To test whether androgen modulates ZFHX3 expression, we determined ZFHX3 expression in AR‐positive prostate cancer cell line LNCaP and its derivative C4‐2B under the treatment of the R1881 synthetic androgen." (PMID 34953044, 2022). "To overcome the clinical obstacle of anti-AR treatment resistance, we hypothesized that eliminating AR protein from prostate cancer cells might completely shut down AR signaling, leading to cell death or growth arrest." (PMID 35372068, 2022). "To determine whether metformin alters proliferation of castration-resistant prostate cancer cells that express AR, we examined the effects of metformin on the AR-positive C4–2 and 22Rv1 human prostate cancer cells." (PMID 36175875, 2022). "During the last years, the improvement in the molecular characteristics of prostate cancer has increased the relevance for a biomarker-driven therapeutic approach and, in this sense, the role of continuing AR signaling during the oncological progression as a key pathway." (PMID 36551557, 2022). "Here, we report that in prostate cancer cells, differential binding of AR and HOXB13 on account of varying MYC levels centers on genes regulated by KMT2A/MLL1, which in turn is inversely proportional to the expression of PLA2G4F in cohorts of advanced, but not localized, PCa." (PMID 36181613, 2022). "Over the past 70 years, the role of AR in prostate cancer have been well studied and characterized." (PMID 35053220, 2022). "Gartanin reduces the AR expression in prostate cancer cells and suppresses AR function." (PMID 36497321, 2022).
prostate carcinoma (continued). "For example, AR signaling is responsible for prostate cancer progression by inducing autophagy." (PMID 35317831, 2022). "CD147 has been reported to modulate androgen receptor activity in prostate cancer cells." (PMID 35625643, 2022). "Since prostate cancer is often dependent on AR, it has become a significant therapeutic target." (PMID 36613955, 2022). "On the other hand, HOXB13 transcripts are downregulated in mCRPC relative to primary prostate cancer, which suggests that its involvement in modifying the AR cistrome may be more relevant to early stages of the disease." (PMID 36212399, 2022). "The current study adds to an increasingly significant body of literature identifying that resistance to AR-targeted therapy may arise, in part, because of inhibiting AR function in the vascular endothelium, as well as within malignant prostate cancer cells." (PMID 35302608, 2022). "GATA2 interacts with androgen receptor to modulate gene transcription in prostate cancer cells." (PMID 35752837, 2022). "Prostate cancer relies on AR signaling in both disease initiation and progression." (PMID 35935969, 2022). "αVβ6 integrin expression negatively correlates with androgen receptor levels in prostate cancer." (PMID 35188070, 2022). "Conversely, the expression of SOCS2-AS1 was increased in castration-resistant prostate cancer model cells where it induced androgen signaling through an epigenetic mechanism involving the regulation of AR target genes and resulted in castration-resistant and androgen-dependent cell growth." (PMID 35641855, 2022). "Importantly, since the discovery that prostate cancer is reliant on androgen signaling to thrive, targeting AR activity continues to be the main pillar of prostate cancer therapy." (PMID 35562350, 2022). "A hypothesis was put forward that zinc finger proteins may have an influential relationship with AR and telomere, which form a triad that controls the pattern of gene expression during the progression of prostate cancer." (PMID 35538543, 2022). "Finally, GATA2, another pioneer transcription factor, is crucial for the activation of AR signaling in prostate cancer." (PMID 36212399, 2022). "Androgen receptor (AR) signaling drives prostate cancer (PC) progression." (PMID 35428760, 2022). "Thus, our data suggest that apigetrin exerts anti-cancer effects by inhibiting AKT, a central key of HIF-1α and AR signaling, in early-and late-stage prostate cancer cells." (PMID 35740392, 2022). "Therefore, ERG and AR overexpression result in prostate cancer cells having increased tolerance to androgen receptor antagonists." (PMID 35563163, 2022). "Collectively, these results suggest that FKBP51 and FKBP52 might be promising targets for prostate cancer treatment through the inhibition of AR dimer formation." (PMID 34057812, 2022). "In prostate cancer, enzalutamide was shown to kill cancer cells by decreasing AR activity." (PMID 36235203, 2022). "Interestingly, activity of these enzyme results strongly linked the tumorigenic potential of androgen receptor (AR)-expressing cancer cells, in line with the known involvement of this HMT in AR signaling in prostate cancer cells." (PMID 35495127, 2022). "AR is a key driver of early and late-stage prostate cancers." (PMID 36175875, 2022). "AR is commonly targeted in prostate cancer, where anti-androgens are relatively effective." (PMID 35158750, 2022).